RNU6-1115P (RNA, U6 small nuclear 1115, pseudogene)
Gene: Small nuclear RNA gene on chromosome 6 (110,856,417 to 110,856,522, forward strand). Ensembl gene ENSG00000199360.
Homologues: Orthologues: chimpanzee U6 (97% identical), macaque U6 (91% identical), dog U6 (67% identical). Paralogues in human: RNU6-1044P (78% identical), RNU6-11P (77% identical), RNU6-16P (77% identical), RNU6-33P (77% identical), RNU6-37P (77% identical), RNU6-48P (77% identical), RNU6-605P (77% identical), RNU6-7 (77% identical), RNU6-8 (77% identical), RNU6-1 (76% identical), RNU6-1020P (76% identical), RNU6-116P (76% identical), and 1285 more.